TRAJ43 (T cell receptor alpha joining 43)
Gene: T-cell receptor joining (J) gene on chromosome 14 (22,495,913 to 22,495,966, forward strand). Ensembl gene ENSG00000211846.
Diseases named in the same sentence as TRAJ43 in open-access papers:
TRAJ43 is named in the same sentence as 1 disease in open-access papers, as found by Europe PMC text mining. Sharing a sentence is not in itself a finding about the gene and the disease.
TRAJ43 shares sentences with these, for which no sentence is quoted: COVID-19 (1 paper).